TET2 (tet methylcytosine dioxygenase 2)
Diseases named in the same sentence as TET2 in open-access papers (continued):
Sharing a sentence is not in itself a finding about the gene and the disease.
steatosis (3 papers, 2020 to 2023). Increased lipid within the cytoplasm of cells. "This was consistent with a dramatic increase in the hepatic TG contents and steatosis in Tet2 knockdown liver." (PMID 37282749, 2023). "The preventive effect of empagliflozin on PA and HG-induced steatosis was abolished when TET2 was knocked-down." (PMID 33551821, 2020). "Both empagliflozin and AICAR increased TET2 in the hepatocyte steatosis model." (PMID 33551821, 2020). "In contrast, Compound C decreased the levels of TET2, ATG5, and Beclin-1 and increased p62 in the hepatocyte steatosis model." (PMID 33551821, 2020). "Compared with the control group, the mRNA and protein levels of TET1 in the two steatosis cell lines were significantly decreased, while the mRNAs of TET2 and TET3 were not significantly changed." (PMID 32577122, 2020). "Also, under the depletion of TET2, autophagy was no longer activated by empagliflozin in the hepatocyte steatosis model, based on the levels of Beclin-1, ATG5, and p62." (PMID 33551821, 2020).
T cell neoplasms (3 papers, 2014 to 2020). "In addition to epigenetic modifiers implicated in all subtypes of T-cell neoplasm (TET2, DNMT3A, KMT2D, KMT2C, SETD2), recurrent mutations of the FAT1 tumor suppressor gene were for the first time recorded in 39% of cases." (PMID 31028364, 2020). "However, few mutations of TET2 have been observed in other B cell neoplasms and more in T cell neoplasms." (PMID 27980696, 2016).
Thrombocytosis (3 papers, 2021 to 2025). Increased numbers of platelets in the peripheral blood. "Co-expression of SF3B1 with DNMT3A, TET2 or ASXL1 promotes myelodysplasia with ring sideroblasts, while acquisition of JAK2 mutations, and less frequently MPL (4%) and SH2B3 (4%) mutations, constitute secondary events that promote thrombocytosis and contribute to the myeloproliferative phenotype." (PMID 33925681, 2021).
thyroid MALT lymphoma (3 papers, 2021 to 2025). "TET2 mutations are frequently found in MALT lymphoma of the thyroid (62%) and will be discussed later." (PMID 35008340, 2021). "The TET2 mutations seen in thyroid MALT lymphoma were very similar to those found in AITL." (PMID 34021249, 2021). "We correlated TET2, TNFRSF14, CD274 and TNFAIP3 mutation AAF in thyroid MALT lymphoma in order to understand the sequence of their occurrence." (PMID 34021249, 2021). "We found frequent deleterious mutations of TET2 (86%), CD274 (53%), TNFRSF14 (53%), and TNFAIP3 (30%) in thyroid MALT lymphoma." (PMID 34021249, 2021). "If this conventional approach fails, somatic mutation analysis should assist their differential diagnosis, in light of the remarkable differences in the mutation profile between thyroid MALT lymphoma and follicular lymphoma, particulalry the highly frequent CD274 and TET2 mutations in the former." (PMID 34021249, 2021). "Recent molecular studies have started to identify genetic changes, like those in TET2 and TNFRSF14, that may explain the biology of thyroid MALT lymphoma." (PMID 41583202, 2025).
type 1 diabetes (3 papers, 2019 to 2024). "In pancreas beta cells, eliminating TET2 reduced pathological immune cell activation and beta cell killing during type 1 diabetes." (PMID 38216792, 2024).
age (2 papers, 2023 to 2025). A temporal measurement of the time period elapsed since an identifiable point in the life cycle of an organism. "In contrast, variants in genes most common in age-related CH, DNMT3A and TET2, were relatively infrequent (3 of 144, 2.1%, and 4 of 144, 2.8%, respectively) and occurred at median age of 59 years (range 47–70), generally in line with their occurrence in the general population." (PMID 40179146, 2025).
anaplastic large cell lymphoma (2 papers, 2025). Anaplastic large cell lymphoma (ALCL) is a rare and aggressive peripheral T-cell non-Hodgkin lymphoma, belonging to the group of CD30-positive lymphoproliferative disorders, which affects lymph nodes and extranodal sites. "Notably, 3 of these patients had early clonal hematopoiesis data available, and one patient had previously been diagnosed with Anaplastic Lymphoma Kinase 1-negative Anaplastic Large Cell Lymphoma (ALK1-ALCL), with the shared TET2 clone present between all these conditions." (PMID 41451201, 2025).
Anxiety (2 papers, 2020 to 2023). Intense feelings of nervousness, tension, or panic often arise in response to interpersonal stresses. "Studies have found that the reduction of 5-hmC is associated with anxiety-like behaviors, in which TET2 plays a key role." (PMID 38012545, 2023).
Arterial thrombosis (2 papers, 2024 to 2025). The formation of a blood clot inside an artery. "In the whole cohort of patients, molecular classification identified PV/ET patients at higher risk of disease progression whereas DNMT3A/TET2/ASXL1 mutations were associated with higher risk of arterial thrombosis." (PMID 38263537, 2024).
bacterial pneumonia (2 papers, 2024). Acute infection of the lung parenchyma caused by bacteria (e.g., Streptococcus pneumoniae, Haemophilus influenzae, Chlamydia pneumoniae, Mycoplasma pneumoniae, and Legionella pneumophila). "The research presented here suggests that naturally occurring mutations in TET2 are a major risk factor for bacterial pneumonia, driven by myeloid immune cell dysfunction." (PMID 38573824, 2024). "Individuals with TET2-mutant clonal hematopoiesis of indeterminate potential are at increased risk of bacterial pneumonia due to innate immune impairments." (PMID 38573824, 2024). "Beyond linking CHIP to bacterial pneumonia risk, they also connect Tet2 mutations to myeloid dysfunction, including hyperinflammation and impaired antibacterial function, setting up CHIP as a potential driver of inflammaging and immune senescence." (PMID 38828722, 2024). "The study identified dysfunction in the monocytic and neutrophilic compartment in the absence of Tet2; however, the mechanism driving increased susceptibility to bacterial pneumonia remains unclear." (PMID 38828722, 2024). "Using characterization of immune cells from human donors and mice lacking tet methylcytosine dioxygenase 2 (Tet2), the authors mechanistically link myeloid immune cell dysfunction to CHIP-mediated risk of bacterial pneumonia." (PMID 38828722, 2024).
brain injury (2 papers, 2021). Acute and chronic (see also brain INJURIES, CHRONIC) injuries to the brain, including the cerebral hemispheres, CEREBELLUM, and brain STEM. "Our previous study showed that the levels of 5hmC were increased, and TET2 protein deletion could increase the Infarct volume after ischemic brain injury." (PMID 34799994, 2021).
cardiac arrest (2 papers, 2024 to 2025). Cessation of breathing and/or cardiac function. "TET2 and ASXL1 mutations are common CHIP mutations predisposing to cardiac arrest, with inflammation and myocardial remodeling proposed as the main pathogenetic mechanisms." (PMID 40804878, 2025).
cervical cancer (2 papers, 2020 to 2023). A primary or metastatic malignant neoplasm involving the cervix. "Demethylation of this gene by TET2 in cervical cancer cell lines decreases cell growth, viability, and colony formation." (PMID 32559232, 2020).
chondrosarcoma (2 papers, 2017 to 2025). A malignant cartilaginous matrix-producing mesenchymal neoplasm arising from the bone and soft tissue. "Although the current data do not establish causality, these findings raise the possibility that TET2-related epigenetic changes may influence oncogenic signaling and tumor progression in chondrosarcoma." (PMID 41290745, 2025).
clear cell renal cell carcinoma (2 papers, 2025). "Clinically, activation of TET2-mediated chemokine expression enhances immunotherapy, while loss of TET2 compromises the exceptional effect of vitamin C on VHL-deficient clear cell renal cell carcinoma." (PMID 40473594, 2025).
cognitive decline (2 papers, 2023 to 2025). "Interestingly, recent work in AD mouse models demonstrated that transplantation of TET2-mutant, but not DNMT3A-mutant, bone marrow-derived cells reduced cognitive decline and Aβ production, suggesting a causal association between TET2-mutations, clonal hematopoiesis, and cognitive resilience." (PMID 41293128, 2025).
colon adenocarcinoma (2 papers, 2024). "To further investigate TET2 expression at the protein level, we analyzed colon adenocarcinoma, normal colon tissue, rectal adenocarcinoma, and normal rectum tissue using data from the HPA database." (PMID 38356721, 2024). "Similarly, there was a positive correlation between TET2 activity and these 3 MHC I antigen-presenting genes in colon adenocarcinoma patients." (PMID 39388288, 2024).
developmental delay (2 papers, 2018 to 2021). "However, Tet1 or Tet2 -null mice are viable and overtly normal double Tet1/Tet2-deficient mice are also obtained, but, some Tet1-deficient mice display a smaller body size at birth, which might reflect a developmental delay." (PMID 33834024, 2021).
emphysema (2 papers, 2025). "With regard to respiratory disease, TET2 knockout in blood cells influences pulmonary inflammation and exacerbates the development of emphysema in mice." (PMID 40525786, 2025). "Mouse Tet2‐mutant CHIP models with COPD further show that Tet2 loss in hematopoietic cells enhances pulmonary inflammation, increases IFN signaling, decreases TGF‐β signaling, and accelerates the development of emphysema." (PMID 40517440, 2025).
Endometrioid endometrial adenocarcinoma (2 papers, 2022 to 2024). "In another study, we compared TET2 level between different histopathological samples (Endometrioid endometrial adenocarcinoma, Serous endometrial adenocarcinoma, Mixed serous and endometrioid)." (PMID 38515066, 2024). "The results showed that the level of TET2 was significantly different among different histopathological samples, and it was significantly over-expressed in endometrioid endometrial adenocarcinoma." (PMID 38515066, 2024). "The results showed that the expression of TET2 was also significantly different among different histopathological samples, and it was significantly over-expressed in Endometrioid endometrial adenocarcinoma (P< 0.05)." (PMID 35480097, 2022). "Thus, we examined the levels of TET2 and 5hmC in endometrioid endometrial adenocarcinoma tissues." (PMID 35480097, 2022).
epilepsy (2 papers, 2022 to 2025). A brain disorder characterized by episodes of abnormally increased neuronal discharge resulting in transient episodes of sensory or motor neurological dysfunction, or psychic dysfunction. "In addition, the manipulation of P-gp expression and functionality by TET2 in a BBB model underlies its involvement in the progression of pharmacoresistant epilepsy." (PMID 35235761, 2022). "In patients with drug‐resistant epilepsy, TET2 expression in the temporal lobe cortex is considerably elevated, especially within vascular regions." (PMID 40599235, 2025). "This study aims to demonstrate the significant expression of TET2 in the cerebrovascular tissue of drug-resistant epilepsy." (PMID 35235761, 2022). "Thus, the chronic epilepsy model exposed to glutamate seem to be a reasonable option to investigate the latent inflammatory framework of TET2 and its relationship with pharmacoresistance and BBB dysfunction." (PMID 35235761, 2022). "TET2 depletion results in the inhibition of ABCB1 in the blood–brain barrier, a dominant pathological gene in epilepsy." (PMID 40599235, 2025).
erythroleukemia (2 papers, 2021 to 2023). Acute erythroid leukemia characterised by the presence of at least 50% erythroid precursors and at least 20% myeloblasts in the bone marrow. "HEL cells, derived from a 30-year-old male with erythroleukemia, have a complex hypotriploid karyotype with 60–64 chromosomes and are reported to carry a monoallelic TET2 gene deletion." (PMID 36480300, 2023).
hypercholesterolaemia (2 papers, 2023 to 2025). "When stimulated with low-density lipoprotein, Tet2-deficient macrophages in atherosclerotic plaque produce more IL-1 and IL-6 compared to macrophages without Tet2 mutations, suggesting that hypercholesterolaemia may intensify the proinflammatory effects of CHIP." (PMID 40076674, 2025). "Tet2‐deficient macrophages in the atherosclerotic plaque produce more IL‐1 and IL‐6 when stimulated with low‐density lipoprotein compared with macrophages without Tet2 mutations, suggesting that hypercholesterolemia may increase the proinflammatory effects of CHIP." (PMID 37489738, 2023).
hypopharyngeal cancer (2 papers, 2018 to 2019). Carcinoma, predominantly squamous cell, arising from the epithelial cells of the hypopharynx. "TET1 was methylated in 34 (59.6%), TET2 in 5 (8.8%), and TET3 in 15 (26.3%) of the 57 hypopharyngeal cancers examined." (PMID 29849955, 2018).
infertile (2 papers, 2020 to 2023). "The gene expression analysis revealed significant changes in the endometrium regarding the genes associated with cell death (BAK1), epigenetic DNA modification (TET2) and the immune response (IL-6) which were upregulated in females with the diagnosed unexplained infertility." (PMID 37576599, 2023).
inflammatory bowel disease (2 papers, 2024 to 2026). A spectrum of small and large bowel inflammatory diseases of unknown etiology. "In inflammatory bowel disease (IBD), persistent cytokine exposure may select for pro-inflammatory clones, with TET2-mutant CHIP linked to severe disease phenotypes." (PMID 42268520, 2026).
ischemia (2 papers, 2023 to 2024). A hypoperfusion of the BLOOD through an organ or tissue caused by a PATHOLOGIC CONSTRICTION or obstruction of its BLOOD VESSELS, or an absence of BLOOD CIRCULATION. "Therefore, we hypothesized that ischemia-related pathologic stimuli may regulate the production of 5-hmC, and TET2 may be involved in mediating the function of ECs in ischemic diseases." (PMID 36658614, 2023).
liver fibrosis (2 papers, 2024 to 2026). "Clonal hematopoiesis driven by Tet2 deficiency in myeloid cells (TetΔMye) is prevalent in elderly individuals; however, the role of Tet2ΔMye in liver fibrosis pathogenesis remains elusive." (PMID 41474968, 2026). "This question gains heightened significance in the context of aging, where the concurrent rise in Tet2 mutation prevalence and liver fibrosis incidence underscores the urgent need to elucidate these mechanisms for potential therapeutic interventions." (PMID 41474968, 2026). "Our study establishes that myeloid-specific Tet2 deficiency exacerbates liver fibrosis through the Ccl2/Ccl8–pMDMs–IL-6–HSCs axis, with Tet2−/− pMDMs driving chemokine production, MDMs infiltration, and HSCs activation." (PMID 41474968, 2026). "To elucidate the mechanism through which Tet2-deficient myeloid cells exacerbate liver fibrosis, we established a competitive myeloid chimeric mouse model through transplantation." (PMID 41474968, 2026). "However, the specific impact of Tet2 deficiency on liver fibrosis, particularly in the context of aging and myeloid hematopoiesis, remains poorly understood." (PMID 41474968, 2026). "In summary, Tet2-deficient myeloid cells may accelerate liver fibrosis by promoting the intrahepatic expansion and pro-inflammatory polarization of Tet2−/− MDMs." (PMID 41474968, 2026). "Third, elevated levels of CCL2 and CCL8 were detected in the serum of elderly liver fibrosis patients carrying TET2 mutations, supporting the clinical relevance of a TET2–CCL2/8 regulatory axis in human disease, which provide a mechanistic basis for the potential clinical application of Bindarit." (PMID 41474968, 2026). "Because of the pivotal role of myeloid cells during liver fibrosis and the age-associated accumulation of Tet2 mutations in myeloid cells, a critical question arises: Does Tet2ΔMye-driven myeloid cell skewing exacerbate fibrosis progression during chronic liver injury?" (PMID 41474968, 2026). "Notably, TET2 mutations were present in 3 of 14 (21.4%) patients with liver fibrosis." (PMID 41474968, 2026). "Our study provides novel insights into how myeloid-specific Tet2 deficiency exacerbates liver fibrosis through the Ccl2/Ccl8–pMDMs–IL-6–HSCs axis, offering a potential therapeutic avenue for targeting fibrosis in populations with abundant aging individuals with TET2 mutations." (PMID 41474968, 2026). "Previous studies have demonstrated that TET2 mutation–induced CHIP is positively correlated with both aging and the progression of advanced liver fibrosis." (PMID 41474968, 2026). "This expands the current understanding of Tet2’s role in myeloid hematopoiesis and highlights its potential as a therapeutic target in liver fibrosis." (PMID 41474968, 2026). "Collectively, these findings demonstrate that myeloid-specific, but not hepatocyte-specific, Tet2 deletion exacerbates CCl4-induced liver fibrosis in mice, highlighting the cell type–specific role of Tet2 in liver fibrogenesis." (PMID 41474968, 2026). "To investigate whether Tet2ΔMye in aging hosts exacerbates liver fibrosis through the Ccl2/Ccl8–pMDMs–HSCs axis, we established a competitive bone marrow transplantation (BMT) model using Tet2-deficient BMCs." (PMID 41474968, 2026). "Furthermore, individuals with TET2Mut CHIP exhibited significantly more advanced liver fibrosis and relatively higher levels of Ccl2 and Ccl8 in serum compared with TET2 WT (TET2WT) counterparts, even after adjusting for co-occurring mutations." (PMID 41474968, 2026). "Our findings reveal that Tet2−/− pMDMs are a major source of elevated Ccl2 and Ccl8 in Tet2ΔMye-CCl4 mice, and Tet2−/− monocytes showed an increased expression of Ccr2 and Ccr3, which, thus, created a positive feedback loop that amplifies MDMs infiltration and liver fibrosis." (PMID 41474968, 2026).
lung adenocarcinoma (2 papers, 2023 to 2025). A carcinoma that arises from the lung and is characterized by the presence of malignant glandular epithelial cells. "TET2 knockdown has also been shown to markedly enhance the migratory, invasive, and proliferative properties of lung adenocarcinoma cells in vitro through activation of the cGAS‐STING signaling pathway." (PMID 40116537, 2025). "There is also evidence to suggest that a reduction in TET2 protein results in increased angiogenesis in lung adenocarcinoma tumor samples through upregulation of VEGFa transcript, allowing for increased tumor growth and thus driving aggressive disease." (PMID 40116537, 2025).
lung disease (2 papers, 2020 to 2025). "Future studies will need to determine whether the relationship between TET2 mutations and COPD is mediated by smoking, or whether loss of function of TET2 plays a contributing role in the exacerbation of pulmonary diseases." (PMID 31963585, 2020).
lymphoid leukemia (2 papers, 2017 to 2022). A malignant lymphocytic neoplasm of B-cell or T-cell lineage involving primarily the bone marrow and the peripheral blood. "TET2 activity and 5hmC levels were shown to be reduced in AML, MDS, CMML, lymphocytic leukemia, and other hematological malignancies." (PMID 28407691, 2017).